LINC00243 (long independently transcribed non-coding RNA 243)
Synonyms: bQB230F21.2; FLJ40693; bQB10J12.2; C6orf214; NCRNA00243
Gene: Long non-coding RNA gene on chromosome 6 (30,797,678 to 30,830,659, reverse strand). Ensembl gene ENSG00000214894.
Diseases named in the same sentence as LINC00243 in open-access papers:
LINC00243 is named in the same sentence as 2 diseases in open-access papers, as found by Europe PMC text mining. Sharing a sentence is not in itself a finding about the gene and the disease. The quoted sentences say what the papers report.
acute appendicitis (1 paper, 2025). "And we found that five genes C4A, FLOT1, LINC00243, MICB, and PRSS16 shared the same tissues between MDD and acute appendicitis." (PMID 41438618, 2025). "Finally, the colocalization analysis identified five shared pleiotropic genes for MDD and acute appendicitis: C4A, FLOT1, LINC00243, MICB, and PRSS16." (PMID 41438618, 2025). "Additionally, through the colocalization analysis, we identified five shared pleiotropic genes between MDD and acute appendicitis: C4A, FLOT1, LINC00243, MICB, and PRSS16." (PMID 41438618, 2025). "Finally, we defined three shared genes: PRSS16, ZNF602P, and ZNF204P by TWAS and nine pleiotropic genes C4A, FLOT1, LINC00243, MICB, and PRSS16 by colocalization analysis between MDD and acute appendicitis." (PMID 41438618, 2025).
tumor (1 paper, 2018). "Compared with the normal group, the expression levels of the most significant four lincRNAs (LINC01088, LINC01018, LINC01436 and LINC00243) were remarkably down-regulated in the tumor group, and the down-regulation of LINC01088 was the most marked." (PMID 29440672, 2018).